GPSM1 (G protein signaling modulator 1)
Description:
Guanine nucleotide dissociation inhibitor (GDI) which functions as a receptor-independent activator of heterotrimeric G protein signaling. Keeps G(i/o) alpha subunit in its GDP-bound form thus uncoupling heterotrimeric G proteins signaling from G protein-coupled receptors. Controls spindle orientation and asymmetric cell fate of cerebral cortical progenitors. May also be involved in macroautophagy in intestinal cells. May play a role in drug addiction.
Synonyms: AGS3; DKFZP727I051
Tractability: Antibody: its Gene Ontology location is reachable by antibodies, with high confidence; UniProt places it where antibodies can reach, with medium confidence. PROTAC: ubiquitination databases record sites on it; its protein half-life has been measured.
Gene: Protein-coding gene on chromosome 9 (136,327,476 to 136,359,605, forward strand). Ensembl gene ENSG00000160360.
Subcellular location: Cytoplasm, cytosol; Endoplasmic reticulum membrane; Golgi apparatus membrane; Cell membrane
Subcellular location (Human Protein Atlas): Golgi apparatus; Nucleoplasm
Pathways (Reactome):
Signal Transduction: G alpha (i) signalling events
Gene Ontology:
Molecular function: GDP-dissociation inhibitor activity; protein binding; G-protein alpha-subunit binding; GTPase regulator activity
Biological process: negative regulation of GTPase activity; negative regulation of guanyl-nucleotide exchange factor activity; positive regulation of macroautophagy; asymmetric cell division; establishment of mitotic spindle orientation
Cellular component: cell cortex; endoplasmic reticulum membrane; Golgi apparatus; Golgi membrane; plasma membrane; protein-containing complex; cytosol
Genetic constraint (gnomAD): Loss-of-function variants: 46 observed, 60.08 expected, observed/expected ratio (o/e) 0.77, 90% interval 0.6 to 0.98. The upper end of that interval is the gene's LOEUF score, 0.98, which puts it in group 4 of 6, group 1 being the genes least tolerant of losing a copy. Missense variants: 931 observed, 872.38 expected, observed/expected ratio (o/e) 1.07, 90% interval 1.01 to 1.13. Synonymous variants: 396 observed, 376.04 expected, observed/expected ratio (o/e) 1.05, 90% interval 0.97 to 1.14.
Homologues: Orthologues: macaque GPSM1 (99% identical), chimpanzee GPSM1 (98% identical), rat Gpsm1 (91% identical), mouse Gpsm1 (90% identical), pig GPSM1 (89% identical), dog GPSM1 (89% identical), guinea pig GPSM1 (87% identical), tropical clawed frog gpsm1 (70% identical), zebrafish gpsm1b (59% identical), Drosophila melanogaster pins (45% identical), zebrafish gpsm1a (13% identical). Paralogues in human: GPSM2 (57% identical), TTC28 (31% identical), TTC24 (16% identical), RAPSN (12% identical), TTC29 (11% identical), GPSM3 (7% identical).
Diseases named in the same sentence as GPSM1 in open-access papers:
GPSM1 is named in the same sentence as 30 diseases in open-access papers, as found by Europe PMC text mining. Sharing a sentence is not in itself a finding about the gene and the disease. The quoted sentences say what the papers report.
Insulin resistance (4 papers, 2022 to 2025). Increased resistance towards insulin, that is, diminished effectiveness of insulin in reducing blood glucose levels. "It showed a genetic risk for obesity, a higher PRS for lipodystrophy, and a significant association with GPSM1, which has been extensively studied for its impact on obesity, insulin resistance, and diabetes." (PMID 40191259, 2025). "Consistently, heterozygous TNFAIP3 depletion reversed the improved glucose metabolic abnormalities and insulin resistance resulting from GPSM1 deficiency, as revealed by glucose-tolerance tests and insulin-tolerance tests." (PMID 36434066, 2022). "It is demonstrated that the transcription of Tumor Necrosis Factor α-Induced Protein 3 (TNFAIP3) is altered, leading to the promotion of metabolic inflammation through the ablation of GPSM1 in a mouse model of high-fat diet-induced insulin resistance." (PMID 38989000, 2024). "We report an important function of the macrophage GPSM1 in the control of metabolic inflammation and systemic insulin resistance and metabolic disturbance in mouse models." (PMID 36434066, 2022). "Mice with myeloid-specific GPSM1 ablation are protected against high fat diet-induced insulin resistance, glucose dysregulation, and liver steatosis via repression of adipose tissue pro-inflammatory states." (PMID 36434066, 2022).
breast carcinoma (3 papers, 2015 to 2021). "Similar analyses of GPSM1, GPSM3, and GPSM4 showed that their related biological pathways are only minimally linked to breast cancer development." (PMID 34572330, 2021). "In our study, analyses from Oncomine and UALCAN suggested different results: GPSM1 was found to be under-expressed in breast cancer in the former database, while the latter indicated the reverse." (PMID 34572330, 2021). "For GPSM1, this result was not consistent with that from Oncomine and the Human Protein Atlas, which indicated that GPSM1 was under-expressed and had low protein expression status in individuals with breast cancer." (PMID 34572330, 2021). "Previous studies have reported the role of GPSM1 and GPSM2 in several cancers, including hepatocellular carcinoma, pancreatic cancer, and breast cancer." (PMID 34827528, 2021). "Furthermore, analysis revealed that GPSM1 had weak protein expression, in contrast to the moderate expression of GPSM2 in clinical breast cancer specimens." (PMID 34572330, 2021). "For example, “prolactin/ERK (extracellular signal-regulated kinase) signaling in breast cancer” was ranked ninth among GPSM1 statistically significant pathway analysis, and “mitogenic action of ESR1 (Estrogen Receptor 1) (membrane) in breast cancer” was ranked 15th for GPSM4." (PMID 34572330, 2021).
diabetes (3 papers, 2021 to 2025). "AP3S2 and GPSM1 have also associated to diabetes and other metabolic disorder by impairing the function of Golgi vesicles formation and trafficking to lysosomes and cell signaling respectively." (PMID 36037214, 2022). "Recent studies have identified GPSM1 as a predisposition gene of premature ovarian insufficiency, a plausible gene involved in regulation of skeletal muscle in diabetes mellitus, and to be overexpressed in prostate adenocarcinoma." (PMID 34572330, 2021).
Obesity (2 papers, 2022 to 2025). Accumulation of substantial excess body fat. "Here, we demonstrate that myeloid GPSM1 promotes metabolic inflammation to accelerate T2D and obesity development." (PMID 36434066, 2022). "IHC staining and qPCR analysis revealed that expression of GPSM1 was substantially higher in visceral fat from the subjects with overweight or obesity (BMI ≥ 24) than that from the subjects with normal BMI (BMI < 24)." (PMID 36434066, 2022). "Of clinical significance, GPSM1 level is increased in the visceral fat of individuals with overweight or obesity, so that it is a potential therapeutic target for metabolic disorders." (PMID 36434066, 2022). "We hypothesized that obesity could similarly lead to GPSM1 activation in macrophages and GPSM1 may serve as a link between inflammation and metabolic homeostasis." (PMID 36434066, 2022). "In summary, obesity upregulates GPSM1 expression in ATMs, suggesting that GPSM1 may be involved in obesity-associated inflammation." (PMID 36434066, 2022). "To further investigate whether GPSM1 expression is also increased in human obesity, we analyzed its expression in visceral fat biopsies of a cohort of individuals with a wide body mass index (BMI) range." (PMID 36434066, 2022). "The roles of other tissue sources of GPSM1 in obesity warrant further investigation." (PMID 36434066, 2022). "To understand the role of GPSM1 in metabolic diseases, we first explored whether obesity impacts GPSM1 expression in mouse models." (PMID 36434066, 2022). "Furthermore, fractionation studies indicated that obesity enhanced GPSM1 exclusively in the stromal vascular fraction (SVF), where ATMs were enriched, but not in the adipocytes of eWAT." (PMID 36434066, 2022). "Moreover, GPSM1 expression is upregulated in WAT from individuals with obesity and correlates with clinical metabolic traits." (PMID 36434066, 2022). "Furthermore, GPSM1 expression is upregulated in visceral fat of individuals with obesity and is correlated with clinical metabolic traits." (PMID 36434066, 2022). "Notably, we observed a positive correlation of expression of GPSM1 in visceral fat with clinical quantitative traits indicating obesity and glucose metabolism, such as BMI, Fasting plasma glucose (FPG), HbA1c, as well as biochemical indicators, including TC, LDL-c, ALT, and AST." (PMID 36434066, 2022). "Thus, we further isolated F4/80+ macrophages from SVFs using F4/80+ microbeads, and we confirmed that obesity could induce GPSM1 overexpression in macrophages." (PMID 36434066, 2022). "Compared to lean controls, mRNA levels of GPSM1 in both epididymal WAT (eWAT) and subcutaneous WAT (scWAT) were significantly higher in mice with high-fat diet (HFD)-induced obesity (DIO) or genetic obesity caused by leptin (Ob/Ob) or leptin receptor (Db/Db) deficiency." (PMID 36434066, 2022). "As obesity progression is associated with high serum FFA levels, and saturated FFAs such as palmitic acid (PA) have greater lipotoxicity, we also investigated whether GPSM1 could mediate NF-κB signaling under PA-induced metabolic stress." (PMID 36434066, 2022).
type 2 diabetes (2 papers, 2022 to 2024). "G-protein-signaling modulator 1 (GPSM1) exhibits strong genetic association with Type 2 diabetes (T2D) and Body Mass Index in population studies." (PMID 36434066, 2022). "G-protein-signaling modulator 1 (GPSM1), an accessory protein which activates heterotrimeric G-protein signaling, exhibits a genetic association with type 2 diabetes." (PMID 36434066, 2022).
acute lymphoblastic leukemia (1 paper, 2021). Leukemia with an acute onset, characterized by the presence of lymphoblasts in the bone marrow and the peripheral blood. "In further experiments, GPSM1 was found to be highly expressed in Acute lymphoblastic leukemia (ALL) cell lines, and downregulation of GPSM1 inhibited proliferation and promoted cell cycle arrest and apoptosis in BALL-1 and Reh cells." (PMID 34257610, 2021).
acute myeloid leukemia (1 paper, 2021). Acute myeloid leukemia (AML) is a group of neoplasms arising from precursor cells committed to the myeloid cell-line differentiation. "The GEPIA results showed that high mRNA expression of GPSM1 was associated with poor overall survival (OS) in acute myeloid leukemia patients (HR = 1.9, p = 0.021)." (PMID 34257610, 2021). "We performed ROC analysis of data from acute myeloid leukemia patients and healthy people to measure the discrimination value of the GPSM1." (PMID 34257610, 2021). "We used UALCAN to analyze GPSM1-related genes in the LAML dataset for acute myeloid leukemia, and the correlation analysis results showed that GPSM1 was positively correlated with ADCY6." (PMID 34257610, 2021).
ependymoma (1 paper, 2020). A WHO grade II, slow growing tumor of children and young adults, usually located intraventricularly. "NOTCH1 and GPSM1 encode membrane proteins critical for Notch signaling and G-protein signaling, respectively, suggesting the involvement of these signaling pathways in ependymoma development in addition to NF-κB pathway that has received the most attention." (PMID 32909151, 2020).
esophageal squamous cell carcinoma (1 paper, 2021). Esophageal squamous cell carcinoma (ESCC) is a type of esophageal carcinoma (EC) that can affect any part of the esophagus, but is usually located in the upper or middle third. "Several studies have shown the association of GPSM1 with the progression of multiple myeloma, prostate cancer and esophageal squamous cell carcinoma, but the role of GPSM1 in the development of leukemia has not been defined." (PMID 34257610, 2021).
Hyperinsulinemia (1 paper, 2022). An increased concentration of insulin in the blood. "HFD GPSM1 deficiency mice had a 1.4-fold elevation of serum adiponectin level and a 56.6% decrease in hyperleptinemia, as well as a 69.7 and a 25.2% decrease in fasting hyperinsulinemia and glucose, respectively, when compared with the levels in the control mice." (PMID 36434066, 2022).
leukemia (1 paper, 2021). A malignant (clonal) hematologic disorder, involving hematopoietic stem cells and characterized by the presence of primitive or atypical myeloid or lymphoid cells in the bone marrow and the blood. "Our findings provide new insights into the molecular details of the GPSM1-associated pathway in leukemia and propose potential therapeutic targets for this disease." (PMID 34257610, 2021). "In the Haferlach Leukemia dataset, the expression levels of GPSM1 in B-ALL, childhood B-ALL and Pro-B ALL were 5.09 (p = 7.08E-67), 5.051 (p = 6.33E-92) and 6.671 (p = 1.31E-40) fold higher than those in PBMCs." (PMID 34257610, 2021). "First, the expression, prognostic value and functional mechanism of GPSM1 in leukemia were analyzed by utilizing certain bioinformatics methods." (PMID 34257610, 2021). "To clarify the prognostic role of GPSM1 in leukemia, we used GEPIA to assess survival." (PMID 34257610, 2021). "Moreover, we observed that GPSM1 was upregulated in BALL-1, Jurkat and Reh leukemia cell lines compared to control cells." (PMID 34257610, 2021). "However, to our knowledge, no studies have investigated the effects of GPSM1 in leukemia." (PMID 34257610, 2021).
leukocytosis (1 paper, 2022). "As leukocytosis and monocytosis promote metabolic inflammation, we first examined whether myeloid GPSM1 loss could affect the proliferation of the Lin−Sca1−cKit+ myeloid progenitors (MPCs) in the bone marrow or blood leukocyte counts and monocyte subset distribution." (PMID 36434066, 2022).
multiple myeloma (1 paper, 2021). "In multiple myeloma, GPSM1 overexpression is correlated with decreased apoptosis." (PMID 34257610, 2021).
steatosis (1 paper, 2022). Increased lipid within the cytoplasm of cells. "The anti-steatosis effects of myeloid GPSM1 knockout were presumably attributed to downregulation of fatty acid uptake genes (CD36, FABP4) and upregulation of fatty acid β-oxidation genes (LCAD) in the liver." (PMID 36434066, 2022).
thyroid cancer (1 paper, 2023). "We found five TAD blocks with CoMut genes/events specific to ATC with certain mutation frequency in The Cancer Genome Atlas Thyroid Cancer (TCGA-THCA) cohort, including CoMut pairs MAST/NSUN4, AM129B/TRUB2, COL5A1/PPP1R26, PPP1R26/GPSM1/CCDC183, and PRAC2/DLX4." (PMID 36609218, 2023).
triple-negative breast carcinoma (1 paper, 2021). An invasive breast carcinoma which is negative for expression of estrogen receptor (ER), progesterone receptor (PR), and human epidermal growth factor receptor 2 (HER2). "GPSM1, GPSM2, and GPSM3 were most highly expressed in triple negative breast cancer cell lines, while GPSM4 showed high expression in multiple luminal A cell lines." (PMID 34572330, 2021).
cancer (4 papers, 2021 to 2023). A tumor composed of atypical neoplastic, often pleomorphic cells that invade other tissues. "The mRNA expression of GPSM1 in 20 types of cancers was compared to that in normal tissues by means of the Oncomine database." (PMID 34257610, 2021).
tumor (3 papers, 2015 to 2021). "The present study demonstrates that GPSM1 promotes tumor growth in BALL-1 and Reh cells by modulating ADCY6-RAPGEF3-JNK signaling." (PMID 34257610, 2021). "TIMER analysis revealed that GPSM1, GPSM2, and GPSM4 were only slightly correlated with tumor purity and infiltrating lymphocytes (correlation coefficients ranging from approximately −0.3 to 0.2)." (PMID 34572330, 2021).
metabolic disorder (2 papers, 2022). "Nevertheless, the molecular mechanism underlying the effect of GPSM1 on T2D and such metabolic disorders remains unknown." (PMID 36434066, 2022). "Next, to explore the underlying mechanisms of the antagonizing effects of GPSM1 ablation on metabolic disorders, we considered whether myeloid GPSM1 might be coupled to metabolic inflammation." (PMID 36434066, 2022).
GPSM1 also shares sentences with these, for which no sentence is quoted: atherosclerosis (1 paper); cocaine addiction (1); colon cancer (1); hepatocellular carcinoma (1); infection (1); lipodystrophy (1); pancreatic cancer (1); polycystic kidney disease (1); Premature ovarian insufficiency (1); prostate adenocarcinoma (1); prostate carcinoma (1).